C1QTNF3-AMACR (C1QTNF3-AMACR readthrough (NMD candidate))
Gene: Protein-coding gene on chromosome 5 (33,987,174 to 34,124,528, reverse strand). Ensembl gene ENSG00000273294.
Genetic constraint (gnomAD): Missense variants: 294 observed, 355.84 expected, observed/expected ratio (o/e) 0.83, 90% interval 0.75 to 0.91. Synonymous variants: 135 observed, 126.91 expected, observed/expected ratio (o/e) 1.06, 90% interval 0.92 to 1.23.